CMTM4 (CKLF like MARVEL transmembrane domain containing 4)
Diseases named in the same sentence as CMTM4 in open-access papers (continued):
Sharing a sentence is not in itself a finding about the gene and the disease.
cancer (18 papers, 2015 to 2025). A tumor composed of atypical neoplastic, often pleomorphic cells that invade other tissues. "Despite being discovered many years ago, the precise role of CMTM4 in cancer progression and its underlying mechanisms remain largely uncharacterized." (PMID 39948411, 2025). "However, the underlying mechanisms for CMTM4 in regulating angiogenesis in cancer needs further in deep investigation." (PMID 35958549, 2022). "Elucidating the physiological and pathological functions of CMTM4 in cancer progression is essential for developing novel immunotherapeutic strategies." (PMID 40433989, 2025). "Univariate Cox analysis revealed that the expression of CMTM1, CMTM4, CMTM7, and cancer stage were significantly associated with poor prognosis in patients with HCC (p < 0.05)." (PMID 36975415, 2023). "The human chemokine-like factor (CKLF)-like MARVEL transmembrane-domain-containing family (CMTM) plays an important role in human cancer, and CMTM4 is the most conserved member in the CMTM family." (PMID 35220395, 2022). "It was reported that CMTM6 and CMTM4 are directly and/or indirectly regulates the expression of PD-L1 in cancer cells and in different immune cells including DCs, macrophages, and monocytes." (PMID 35958549, 2022). "Taken together, our data provide the first evidence of CMTM6 and CMTM4 expression in canine cancers and their possible involvement in PD-L1 regulation." (PMID 32596272, 2020). "To assess the protein expressions of CMTM6 and CMTM4 in canine cancers, we firstly examined the cross-reactivities of commercially available antibodies against human CMTM6 and CMTM4 using canine CMTM6- or CMTM4-expressing cells." (PMID 32596272, 2020). "CMTM4 is a ubiquitously expressed transmembrane protein that has recently gained attention as a potential contributor to various cancers." (PMID 33614606, 2020). "The expression analysis by qRT-PCR revealed that canine CMTM6 and CMTM4 can be expressed in canine immune cells and cancer cells, both of which are considered important PD-L1 sources in the suppression of antitumor immunity." (PMID 32596272, 2020). "Recent reports have shown that CMTM6 and CMTM4 are critical regulators of PD-L1 protein expression in human cancer cells." (PMID 32596272, 2020). "CMTM4 is tightly linked with CMTM1-3 on chromosome 16q22.1, a genomic region prone to both genetic and epigenetic modifications in various cancers." (PMID 26474560, 2015). "An integrated bioinformatics analysis based on the array data from the GEO database was conducted to view the differential expression of CMTM4 across multiple cancers and their corresponding control tissues." (PMID 26474560, 2015). "Taken together, these studies suggest that CMTM4 may have different roles depending on the cancer type and the role of CMTM4 needs to be delineated in a cancer type specific manner." (PMID 39948411, 2025). "The role of CMTM4 in cancer development has not been fully understood." (PMID 39948411, 2025). "Interestingly, while CMTM4 is expressed only in low and variable amounts in multiple normal human tissues, it is universally expressed in a multitude of human cancers." (PMID 39948411, 2025). "The expression of CMTM6 and CMTM4 correlated heavily with the prognosis of various cancers." (PMID 35958549, 2022). "Therefore, CMTM6 and CMTM4 may be attractive to development novel immunotherapeutic stategy for cancer patients with poor outcomes treated by current methods." (PMID 35958549, 2022). "In this regard, exosomal miR-5703 was found to target CKLF Like MARVEL Transmembrane Domain Containing 4 (CMTM4) which is known to regulate the expression of the inhibitory programmed death-ligand 1 (PD-L1) and to stabilize the PD-L1 receptor in cancers." (PMID 37373351, 2023). "The mRNA expression of CKLF, CMTM1, CMTM3, CMTM4, and CMTM7 was correlated with the cancer stage, revealing that patients with more advanced cancer stages tended to have higher mRNA expression of the CMTM family." (PMID 36975415, 2023).
cancer (continued). "CMTM3, CMTM4, and CMTM5 are thought to bring about favorable prognostic factors in several cancer types." (PMID 35252165, 2022). "Next, we observed that, compared to other cancer types, the difference in CMTM4 expression between OC and normal samples was particularly pronounced, and its expression was indicative of poor prognosis." (PMID 40433989, 2025). "In addition, CMTM4 can regulate the cancer stem cell -like phenotype through the AKT pathway, which would enhance the significance of CMTM4 as a therapeutic target." (PMID 38223763, 2024). "CMTM6 and CMTM4 mRNA expression was detectable in all these samples, suggesting that CMTM6 and CMTM4 are ubiquitously expressed genes in canine immune cells and cancer cells." (PMID 32596272, 2020). "In the immunohistochemical analysis, PD-L1 expression was found in CMTM6- and CMTM4-expresssing cancers, which supports the hypothesis that canine CMTM6 and CMTM4 are involved in the expression of PD-L1." (PMID 32596272, 2020). "CMTM4 KD reduced activation of EGFR/Akt/mTOR and NF-κB pathways, suggesting that different CMTM family members may have distinctly different functions in cancer cells." (PMID 39948411, 2025). "However, the detailed function of CMTM4 on cancer cells has not been explored." (PMID 39948411, 2025).
infection (1 paper, 2015). The state of being infected such as from the introduction of a foreign agent such as serum, vaccine, antigenic substance or organism. "FITC-Annexin V/PI staining indicated that overexpression of CMTM4 did not induce apoptosis of 786-O cells 72 h after infection." (PMID 26474560, 2015).
CMTM4 also shares sentences with these, for which no sentence is quoted: colorectal cancer (2 papers); cholangiocarcinoma (1); colon adenocarcinoma (1); colon cancer (1); esophageal carcinoma (1); experimental autoimmune encephalomyelitis (1); gastric tumor (1); Hypertension (1); intrauterine growth restriction (1); leukemia (1); Lewis lung carcinoma (1); lung squamous cell carcinoma (1); osteosarcoma (1); ovarian carcinoma (1); paraganglioma (1); pheochromocytoma (1); prostate adenocarcinoma (1); prostate carcinoma (1); rectum adenocarcinoma (1); thymoma (1); undifferentiated pleomorphic sarcoma (1).